RN7SL860P (RNA, 7SL, cytoplasmic 860, pseudogene)
Gene: Miscellaneous RNA gene on chromosome 19 (22,601,485 to 22,601,707, forward strand). Ensembl gene ENSG00000240713.
Homologues: Orthologues: chimpanzee Metazoa_SRP (95% identical), guinea pig Metazoa_SRP (62% identical), dog Metazoa_SRP (41% identical). Paralogues in human: RN7SL176P (72% identical), RN7SL736P (72% identical), RN7SL185P (71% identical), RN7SL209P (71% identical), Metazoa_SRP (70% identical), RN7SL536P (69% identical), RN7SL545P (69% identical), RN7SL759P (69% identical), Metazoa_SRP (69% identical), RN7SL106P (69% identical), RN7SL238P (69% identical), RN7SL166P (68% identical), and 709 more.